SNORD116-24 (small nucleolar RNA, C/D box 116-24)
Synonyms: HBII-85-24
Gene: Small nucleolar RNA gene on chromosome 15 (25,094,037 to 25,094,128, forward strand). Ensembl gene ENSG00000207279.
Gene Ontology:
Biological process: RNA processing
Cellular component: nucleolus
Homologues: Orthologues: chimpanzee SNORD116 (100% identical), macaque SNORD116 (92% identical), guinea pig SNORD116 (89% identical), guinea pig SNORD116 (85% identical). Paralogues in human: SNORD116-16 (97% identical), SNORD116-17 (93% identical), SNORD116-19 (93% identical), SNORD116-14 (92% identical), SNORD116-15 (92% identical), SNORD116-18 (92% identical), SNORD116-20 (92% identical), SNORD116-21 (92% identical), SNORD116-22 (92% identical), SNORD116-23 (92% identical), SNORD116-12 (89% identical), SNORD116-13 (89% identical), and 20 more.